LMTK2 (lemur tyrosine kinase 2)
Diseases named in the same sentence as LMTK2 in open-access papers (continued):
Sharing a sentence is not in itself a finding about the gene and the disease.
prostate adenocarcinoma (5 papers, 2010 to 2021). "The data confirm that the risk genotype at the GWAS variant rs6465657 correlates with LMTK2 expression and that prostate adenocarcinoma samples expresses 68% less LMTK2 mRNA than BPH samples, providing strong evidence for the role of this gene in PCa progression." (PMID 34064250, 2021). "Decreased LMTK2 expression was observed in prostate adenocarcinoma as well as in other common malignancies such as lung or skin cancers." (PMID 31748522, 2019). "We determined that levels of LMTK2 transcripts in prostate adenocarcinomas were only 32% of those in benign tissues (p = 3.2 × 10-7), and that an independent effect of genotype at variant rs6465657 on LMTK2 expression in benign (n = 39) and malignant tissues (n = 21) was also evident (P = 0.002)." (PMID 20569440, 2010). "The LMTK2-AR interaction was demonstrated by co-immunoprecipitation and Proximity Ligation Assay (PLA) in LNCaP cells, an androgen-sensitive human prostate adenocarcinoma cell line." (PMID 30761001, 2019).
hepatocellular carcinoma (4 papers, 2019 to 2024). A malignant tumor that arises from hepatocytes. "Similarly, knockdown of LMTK2 inhibited the proliferation of colon cancer cells by inactivating nuclear factor-κB (NF-κB), while LMTK2 silencing repressed the proliferation and invasion of hepatocellular carcinoma cells in vitro through the inhibition of Wnt/β-catenin signalling." (PMID 34064250, 2021). "Due to its high stability, circRNA is an excellent biomarker for human diseases, especially cancer; examples include circ-SMARCA5 as a biomarker for hepatocellular carcinoma, circ-ANKS1B for breast cancer, circ-UBXN7 for bladder cancer and circ-LMTK2 for gastric cancer." (PMID 31631067, 2019).
colorectal cancer (2 papers, 2021 to 2024). A primary or metastatic malignant neoplasm that affects the colon or rectum. "The role of LMTK2 in other pathological processes, such as the lung, gastric, and colorectal cancer as well as infertility has not been well established." (PMID 33816229, 2021).
cystic fibrosis (2 papers, 2014 to 2019). Autosomal recessive disorder caused by pathogenic variants in the CFTR gene (cystic fibrosis transmembrane conductance regulator), which encodes a chloride and bicarbonate channel expressed in epithelial cells, and follow the diagnosis criteria. "Targeting the LMTK2 interactome could also advance treatment for cancer, neurodegeneration, infertility, and cystic fibrosis and create novel strategies for contraception." (PMID 30761001, 2019).
dementia (2 papers, 2019 to 2024). Loss of intellectual abilities interfering with an individual's social and occupational functions. "Immunoblot analysis of tissue lysates has revealed significantly reduced LMTK2 levels in mid dementia (Braak stage III-IV) and sever dementia (Braak stage VI) cases in the cortex compared to controls." (PMID 39520508, 2024). "We studied LMTK2 levels in cortex and cerebellum (affected and non-affected regions) in control, Braak stage III-IV (mid dementia) and Braak stage VI (severe dementia) cases." (PMID 31068217, 2019).
gastric cancer (2 papers, 2019 to 2022). A primary or metastatic malignant neoplasm involving the stomach. "In conclusion, LMTK2 silencing can inhibit the proliferation of gastric cancer cells in vitro and tumor growth in vivo by regulating GSK-3β phosphorylation and β-catenin nuclear translocation." (PMID 34719320, 2022). "A tumor-bearing nude mouse model was established by injecting gastric cancer cells, and the effect of LMTK2 knockdown or overexpression on tumor growth was examined." (PMID 34719320, 2022). "Briefly, LMTK2 silencing can inhibit the proliferation of gastric cancer cells in vitro and tumor growth in vivo by regulating GSK-3β phosphorylation and β-catenin nuclear translocation." (PMID 34719320, 2022). "The expression levels of LMTK2 were upregulated in all gastric cancer cell lines compared with the GEL-1 normal epithelial cells." (PMID 34719320, 2022). "The aim of the present study was to investigate the role of lemur tyrosine kinase 2 (LMTK2) in gastric cancer cell proliferation and cell cycle progression, as well as in tumor-bearing nude mouse models." (PMID 34719320, 2022). "The present study was to investigate the role of LMTK2 in gastric cancer cell proliferation and cell cycle progression, as well as in tumor-bearing nude mouse models." (PMID 34719320, 2022). "In the present study, the effect of LMTK2 on the proliferation of gastric cancer cells was examined, and the possible mechanism was explored." (PMID 34719320, 2022). "Therefore, the aim of the present study was to investigate the role of LMTK2 in gastric cancer cell proliferation and cell cycle progression, as well as in tumor-bearing nude mouse models." (PMID 34719320, 2022). "In conclusion, the expression of LMTK2 in gastric cancer cells was upregulated." (PMID 34719320, 2022). "The expression levels of LMTK2 were found to be upregulated in all gastric cancer cell lines." (PMID 34719320, 2022). "The expression levels of LMTK2 were upregulated in patients with gastric cancer." (PMID 34719320, 2022). "The expression levels of LMTK2 were determined in gastric cancer cell lines." (PMID 34719320, 2022). "The expression levels of LMTK2 were found to be upregulated in gastric cancer cell lines." (PMID 34719320, 2022). "The expression levels of LMTK2 were examined in the GEL-1 normal gastric epithelial cell line and four gastric cancer cell lines (KATO III, HSC-39, AGS and MKN45) using RT-qPCR and western blotting." (PMID 34719320, 2022). "However, the specific role of LMTK2 in gastric cancer remains unclear." (PMID 34719320, 2022).
Infertility (2 papers, 2019 to 2021). "Abnormalities in the expression and function of LMTK2 are associated with human disease, such as neurodegeneration, cancer and infertility." (PMID 30761001, 2019). "The role of LMTK2 in cell signaling, endocytic trafficking, apoptosis, and Cl− transport explains why its dysregulation is associated with neurodegeneration, cancer, and infertility." (PMID 30761001, 2019). "Hence, LMTK2 emerges as a potential target for both reproductive contraceptives, such as an inhibitor of sperm motility, and infertility treatment in men, by regulating the activity of PP1." (PMID 30761001, 2019).
autism spectrum disorder (1 paper, 2024). A spectrum of developmental disorders that includes autism, and Asperger syndrome. "Finally, significant LMTK2 gene expression reductions have been observed in autism spectrum disorder and schizophrenia risk models." (PMID 39520508, 2024).
cervical cancer (1 paper, 2021). A primary or metastatic malignant neoplasm involving the cervix. "In this regard, LMTK2 is known to bind directly to myosin VI in human cervical cancer HeLa cells, permitting the delivery of membrane pumps, channels, and nutrient receptors from the early endosome to the perinuclear endocytic recycling compartment (ERC) and to the plasma membrane." (PMID 34064250, 2021).
deafness (1 paper, 2016). An inherited or acquired condition characterized by the complete loss of the ability to hear from one or both ears. "An myosin VI mutation (3496C > T) that causes deafness in Pakistani families leads to a premature stop in the C-terminal cargo-binding tail domain (at R1166X) and loss of the WWY motif, the binding site for myosin VI adaptor proteins, including Dab2, LMTK2 and Tom1/L2." (PMID 27474411, 2016).
diabetic retinopathy (1 paper, 2011). "Other examples include lemur tyrosin kinase (LMTK2), and nuclear transport factor 2 (NUTF2) involved in cancer susceptibility and diabetic retinopathy, respectively." (PMID 21479260, 2011).
gastric tumor (1 paper, 2022). "Moreover, LMTK2 silencing could inhibit the growth of gastric tumors in vivo." (PMID 34719320, 2022).
lung adenocarcinoma (1 paper, 2019). A carcinoma that arises from the lung and is characterized by the presence of malignant glandular epithelial cells. "Additionally, LMTK2 has been identified as a driver mutation in lung adenocarcinoma by a large-scale RNA-seq analysis.." (PMID 31722712, 2019).
lung carcinoma (1 paper, 2021). "Indeed, this observation corroborates several independent studies showing that LMTK2 is associated with the susceptibility and severity of colon, gastric, prostate and lung cancer." (PMID 33816229, 2021).
lymph node metastasis (1 paper, 2020). "For example, circHECTD1, circ‐LMTK2 (which is encoded by the LMTK2 gene) and circ‐KAA124 were reported to be closely related to lymph node metastasis and TNM stage." (PMID 32515024, 2020).
male infertility (1 paper, 2021). The inability of the male to effect fertilization of an ovum after a specified period of unprotected intercourse. "LMTK2 has been associated with several disorders, including CF, neurodegeneration, male infertility and different types of cancer." (PMID 33816229, 2021).
Neurofibrillary tangles (1 paper, 2025). Pathological protein aggregates formed by hyperphosphorylation of a microtubule-associated protein known as tau, causing it to aggregate in an insoluble form. "They found that LMTK2 expression was significantly reduced in neurofibrillary tangle-affected regions and showed a strong inverse correlation with phospho-tau levels, indicating that decreased LMTK2 is associated with tau pathology rather than a general feature of AD brains." (PMID 41465242, 2025).
sarcoma (1 paper, 2022). A usually aggressive malignant neoplasm of the soft tissue or bone. "STARD3NL::BRAF fusion has earlier been described at least in one paediatric sarcoma, whereas to our best knowledge, LMTK2::BRAF has not been reported before in any tumour type." (PMID 35237889, 2022).
tauopathy (1 paper, 2019). Neurodegenerative disorders involving deposition of abnormal tau protein isoforms (tau proteins) in neurons and glial cells in the brain. "According to our results LMTK2 reduction is specific to AD (or tauopathies), while the moderately decreased immunoreaction in LBD compared to CNT was probably caused by the frequently coexisting AD-type pathology." (PMID 31748522, 2019).
cancer (15 papers, 2010 to 2024). A tumor composed of atypical neoplastic, often pleomorphic cells that invade other tissues. "LMTK2 KD was associated with susceptibility to cancer, organismal injury, and endocrine, gastrointestinal and reproductive system diseases in the TGF-β1 and vehicle control group." (PMID 33816229, 2021). "Bioinformatics analysis shows that LMTK2 is involved in diverse cellular functions and disease pathways, such as cell death and survival, cellular development, and cancer susceptibility." (PMID 33816229, 2021). "In fact, LMTK2 polymorphisms that increase LMTK2 protein levels have been previously reported in cancer in different organs, including the lung, gastrointestinal tract, and prostate." (PMID 33816229, 2021). "Future studies are needed to experimentally validate the diagnostic and prognostic potential of LMTK2 in different forms of cancer." (PMID 30761001, 2019). "Our results confirm the role of LMTK2 in cancer development and susceptibility." (PMID 33816229, 2021). "LMTK2 disorders are involved in a variety of pathological processes, including cancer, infertility, cystic fibrosis and neurodegeneration." (PMID 34719320, 2022). "We observed that LMTK2 influenced the ‘molecular mechanism of cancer’ pathways and that treatment with TGF-β1 enhanced these effects." (PMID 33816229, 2021). "The ‘molecular mechanisms of cancer’ pathway was highly affected by LMTK2 KD in both treatment groups." (PMID 33816229, 2021). "Conti and co-workers showed that LMTK2 silencing sensitises immortalised epithelial and cancer cells to TNF-related apoptosis-inducing ligand (TRAIL) cytotoxicity, by regulating the levels of anti-apoptosis BCL2 family members." (PMID 34064250, 2021). "Our data provide novel evidence for the role of intracellular trafficking events regulated by LMTK2 in modulating the TGF-β1 signaling during cell death and survival, cellular development, and cancer susceptibility." (PMID 33816229, 2021). "While LMTK2-dependent regulation of BIM was more evident in non-cancer cell lines, other members of the BCL2 family, such as BCL2 and BCL-xL, were regulated by LMTK2 mainly in fully transformed cancer cells." (PMID 30761001, 2019). "In addition, the expression levels of LMTK2 in patients with different types of cancer were obtained from the CCLE website." (PMID 34719320, 2022). "All these findings suggest that LMTK2 inhibition might represent a valuable approach in the treatment of specific cancers." (PMID 34064250, 2021). "The role of LMTK2 in apoptosis suggests that its dysregulation may be involved in other forms of cancer as well." (PMID 30761001, 2019). "Role of LMTK2 has been discussed in several malignant tumours." (PMID 31748522, 2019). "In fact, LMTK2 mRNA is expressed in all cancer tissues according to The Cancer Genome Atlas (TCGA)." (PMID 30761001, 2019). "The LMTK2 protein levels differ in a variety of cancer cells." (PMID 30761001, 2019). "LMTK2 plays an important role in modulating the physiological function of a number of organs, including the airways, prostate gland and brain, as well as in the development of various human cancers." (PMID 26559041, 2015). "Thus, future studies may identify potential checkpoints of the LMTK2 pathway amenable for cancer therapeutic targeting." (PMID 33816229, 2021). "The coadministration of TPA and EGCG in cancer model systems might be a promising approach to promote both the synergic inhibition of AR signalling mediated by the LMTK2 inhibitory action and the down regulation of PI3K-Akt-mTOR pathway directly by means of EGCG." (PMID 34064250, 2021). "Recent studies have suggested that LMTK2 may interact with myosin IV, which has been shown to regulate both prostate specific antigen (PSA) and vascular endothelial growth factor (VEGF), both of which are associated with cancer." (PMID 20569440, 2010).
cancer (continued). "Some studies have also detected LMTK2 and LMTK3 in the nucleus in cancer cells, however, other studies which have analysed LMTK subcellular localisation in neurons did not observe LMTKs in the nucleus." (PMID 39520508, 2024). "In summary, our data increase the knowledge on the interplay between LMTK2 and TGF-β1 regulatory networks in certain pathological processes affecting different organ systems, including distinct types of cancer." (PMID 33816229, 2021). "It is interesting that LMTK2 can induce both pro- and anti-inflammatory signalling cascades but it is also important to note that the effect of LMTK2 on NF-κB was tested in some cancer cell lines and not in microglia." (PMID 39520508, 2024).
tumour (9 papers, 2010 to 2024). "Considering LMTK2 as tumour suppressor/pro-apoptotic protein, it is possible that E2F reduces LMTK2 levels by transcriptional silencing." (PMID 29631601, 2018). "LMTK2 knockdown also suppressed tumor growth, whereas overexpression accelerated this process." (PMID 34719320, 2022). "Since, LMTK2 is involved in the sophisticated regulation of apoptotic factors we could consider it as a tumour suppressor protein." (PMID 31748522, 2019). "In GBM, LMTK2 mediates tumor suppression by upregulating RUNX3, which in turn inhibits the Notch signaling pathway; low levels of LMTK2 are associated with poor overall survival, thereby suggesting that both LMTK2 and RUNX3 collectively influence the prognosis of GBM patients." (PMID 38430423, 2024). "Moreover, LMTK2 down-regulation obtained in PCa LNCaP cell line promotes tumour-forming capacity and proliferation, suggesting that the decrease in LMTK2 expression in PCa patients may promote tumour cells’ proliferation by enhancing AR transcriptional activity." (PMID 34064250, 2021).
neurodegenerative disease (2 papers, 2018 to 2024). A disorder of the central nervous system characterized by gradual and progressive loss of neural tissue and neurologic function. "Thirdly, neuroinflammation is also seen in all major neurodegenerative diseases and recent evidence supports such notion that LMTK2 itself is linked to inflammation." (PMID 39520508, 2024). "Assuming that PP1 and GSK3β are also transported to the synapse by the LMTK2-KLC-kinesin-1 motor complex, LMTK2 deficiency can induce further synaptic dysfunction in neurodegenerative diseases by disrupting axonal transport of these important synaptic signalling molecules." (PMID 39520508, 2024). "Therefore, loss of LMTK2 can contribute to microglia activation and neuroinflammation in neurodegenerative diseases by activating GSK3β and blocking the anti-inflammatory effect of Nrf2." (PMID 39520508, 2024). "LMTK2, a brain enriched neuronal kinase has recently become of interest in neurodegenerative disease research since it regulates a number of fundamental cellular pathways linked to neurodegeneration." (PMID 29631601, 2018). "Despite the limited amount of studies in the field, LMTK2 seems to be mis- and downregulated in Alzheimer's, and other neurodegenerative diseases." (PMID 29631601, 2018).
adenocarcinoma (1 paper, 2010). A common cancer characterized by the presence of malignant glandular cells. "We identified a 68% reduction in the expression of the LMTK2 gene in prostate tissue with evidence of the presence of adenocarcinoma when compared with non-malignant BPH samples." (PMID 20569440, 2010).
LMTK2 also shares sentences with these, for which no sentence is quoted: benign prostate hyperplasia (4 papers); breast carcinoma (3); infection (3); colon cancer (2); pancreatic cancer (2); asthma (1); Azoospermia (1); bladder cancer (1); Chronic Lymphocytic Leukemia (1); cutaneous leishmaniasis (1); Glycogen Storage Disease (1); liposarcoma (1); liver cancer (1); prostate hyperplasia (1); reproductive system diseases (1); rheumatoid arthritis (1); schizophrenia (1); thyroid cancer (1); α-synucleinopathies (1).